CASR (calcium sensing receptor)
Diseases named in the same sentence as CASR in open-access papers (continued):
Sharing a sentence is not in itself a finding about the gene and the disease.
Hypocalcemia (continued). "Similarities between familial isolated hypoparathyroidism in humans and the refractory hypocalcemia observed in Thoroughbred foals led to the hypothesis that genetic variants in PTH, GCM2, CASR, GNA11 or TRPM6 may be responsible for the disease in the horse." (PMID 32986719, 2020). "The p.Gly66Ser and p.Arg149His Gα 11 mutations were associated with an overall mild increase in CaSR-mediated Ca2+i and MAPK responses, and these findings may explain the mild hypocalcemia observed in the patients harboring these mutations." (PMID 31820785, 2020). "Whether there is a place for the use of CaSR allosteric modulators in relevant clinical areas, for example, in reducing the degree of hypocalcemia in critically ill patients, remains to be explored." (PMID 27679579, 2016). "The hypocalcemia of critically ill patients with burn injury or sepsis is associated with CASR gene upregulation by TNF-alpha and IL-1beta via kappaB elements, and by IL-6 via Stat1/3 and Sp1/3 elements in the CASR gene promoters, respectively." (PMID 27679579, 2016). "Gain-of-function mutations of the CaSR either cause autosomal dominant hypercalcemia (ADH), which is characterized by hypocalcemia and hypercalciuria, or BS type 5, which in addition is associated with renal salt wasting leading to hyperreninemia, hyperaldosteronism and hypokalemia." (PMID 25506941, 2014). "Importantly, it induced less hypocalcemia than cinacalcet, which might be attributed to biased signaling of the CaSR resulting in less CaSR-mediated calcitonin secretion." (PMID 39676111, 2024). "The similar clinical presentation between familial isolated hypoparathyroidism in humans and equine idiopathic hypocalcemia led to the hypothesis that a coding variant within PTH, GCM2, CASR, GNA11 or TRPM6 would be associated with idiopathic hypocalcemia of TB foals." (PMID 32986719, 2020). "Therefore, such hyperphosphatemia might moderate the gain of function by partially inhibiting the CaSR, so limiting the severity of the hypocalcemia, hypercalciuria, and nephrocalcinosis." (PMID 31619668, 2019). "The in vitro studies revealed that NPS 2143 was effective in rectifying the gain-of-function of the mutant Gln723 CaSR, and we therefore pursued studies to determine whether ip injection of the calcilytic compound NPS 2143 could improve the hypocalcemia associated with Nuf mice." (PMID 26052899, 2015). "The CaSR is expressed on the basolateral membrane of the TALH, and gain of function mutations in CASR may also lead to a salt-wasting phenotype in addition to hypocalcemia." (PMID 24400161, 2013). "Subsequently, low calcitriol levels and hypocalcemia induced by increasing FGF23 levels indirectly stimulate PTH synthesis and release in the parathyroid via VDR and CaSR, overriding the inhibitory action of FGF23." (PMID 35269640, 2022). "As a result, low calcitriol levels and hypocalcemia promote PTH synthesis and release via VDR and CaSR in parathyroid, overriding the inhibitory effect of FGF23." (PMID 35269640, 2022). "Interestingly, our data suggested that the decrease in PTG CaSR expression, which is important in the development of SHPT, was caused by the early decrease in PTG Gcm2 expression, followed by the effect of 1,25(OH)2D reduction, PTG VDR reduction, hypocalcemia and hyperphosphatemia." (PMID 32517664, 2020). "In isolated cases, pathogenic mechanisms include activating autoantibodies against the calcium-sensing receptor (CaSR), which suppresses parathyroid hormone (PTH) secretion despite hypocalcemia, as shown in sporadic patients and in immune checkpoint inhibitor-induced hypoparathyroidism." (PMID 41465179, 2025). "Thus, hypocalcaemia, which results from hyperphosphataemia and diminished 1,25(OH)2D3 synthesis in CKD, disables the parathyroid CaSR, elevating PTH secretion." (PMID 36267284, 2022). "Eight unrelated patients with hypocalcemia and low or inappropriately normal PTH levels in the absence of CASR mutations were studied by Sanger sequencing." (PMID 27803672, 2016).
Hypocalcemia (continued). "To date, it is not possible to explain the etiology behind hypocalcemia during COVID-19 infection, but parathyroid defects that are yet uncovered are highly expectable and a CaSR aberrant over-activity is plausible; therefore, additional investigations into these questions are needed." (PMID 36467702, 2022). "CaSR activation in the basolateral membrane of the intestine directly attenuates local Ca2+ absorption through TRPV6 to prevent hypercalcemia, which may explain how CaMs induce hypocalcemia." (PMID 36015101, 2022). "Hyperphosphatemia, hypocalcemia, low serum vitamin D levels are greatly involved into the physiopathology of SHPT in chronic kidney disease (CKD), in which the down-regulation of parathyroid Vitamin D Receptor (VDR) and Calcium Sensing Receptor (CaSR) represent a critical step." (PMID 25032145, 2014). "However, CaSR is not activated in hypocalcemia, so PTH release is stimulated." (PMID 36651710, 2023). "Considering the biased signaling properties of CaSR, we aimed at identifying and characterizing other positive allosteric modulators of CaSR that might exert NB-specific effects, without inducing clinically relevant hypocalcemia." (PMID 35457141, 2022). "Lastly, given the possible involvement of the CaSR in the pathogenesis of COVID-19 infection, it is tempting to speculate about a possible applicability of calcilytics as effective therapeutics to counteract SARS-CoV-2 infection or, at least, to mitigate hypocalcemia, reducing patients’ morbidities." (PMID 36467702, 2022). "The patient reported by El Kawkgi developed hypocalcemia with low PTH levels during ipilimumab plus nivolumab treatment, but CaSR autoantibodies have not been measured." (PMID 36672478, 2023).
familial hypocalciuric hypercalcemia (80 papers, 2010 to 2025). Familial hypocalciuric hypercalcemia (FHH) is a generally asymptomatic genetic disorder of phosphocalcic metabolism characterized by lifelong moderate hypercalcemia along with normo- or hypocalciuria and elevated plasma parathyroid hormone (PTH) concentration. "The clinical and molecular findings were consistent with familial hypocalciuric hypercalcemia potentially caused by a loss-of-function CASR mutation." (PMID 41155848, 2025). "CASR mutations can be gain-of-function, causing autosomal dominant hypocalcemia type 1, or loss-of-function, leading to familial hypocalciuric hypercalcemia." (PMID 41155848, 2025). "The majority of patients with NSHPT are identified as having homozygous or compound heterozygous pathogenic variants of CASR and many patients have a family history of hypocalciuric hypercalcemia." (PMID 39703927, 2024). "Heterozygous variants in the calcium-sensing receptor gene CASR (pLI = 0.05) can cause hypocalciuric hypercalcemia while autosomal-dominant tubulointerstitial kidney disease can be caused by variants in UMOD (pLI = 0), MUC1 (pLI = 0.02) or REN (pLI = 0)." (PMID 39099563, 2024). "The patient's biochemical profile and the identification of the CaSR variant support the diagnosis of familial hypocalciuric hypercalcemia (FHH)." (PMID 39246902, 2024). "Inactivating germline mutations of CASR are responsible for familial hypocalciuric hypercalcemia and neonatal severe hyperparathyroidism." (PMID 34054720, 2021). "In this study, a novel mutation in the CaSR gene in a patient with hypocalciuric hypercalcemia was identified, and functional analysis was performed to provide a basis for diagnosis and treatment." (PMID 35095753, 2021). "Auto-immune hypocalciuric hypercalcemia is different in pathogenesis from the one caused by inactivating mutations of the CASR." (PMID 34736428, 2021). "The homozygous mutation D99N reduced CaSR activity and caused more severe hypocalciuric hypercalcemia." (PMID 35095753, 2021). "We identified a novel inactivating mutation in the calcium-sensing receptor (CaSR) gene in a patient with refractory hypocalciuric hypercalcemia and analyzed its function." (PMID 35095753, 2021). "Missense mutations in human CaSR gene cause familial hypocalciuric hypercalcemia (FHH) or neonatal severe hyperparathyroidism (NSHPT) dependent on the allele dose." (PMID 32659887, 2020). "Nonetheless the individual carrying this mutation, along with others carrying more dramatic mutations in the signal sequence of CASR, suffered from hypocalciuric hypercalcemia." (PMID 28093506, 2017). "Familial hypocalciuric hypercalcemia (FHH) is caused by inactivating mutations in the calcium-sensing receptor (CaSR) gene." (PMID 28690912, 2017). "Ultimately, genetic analysis revealed a heterozygous mutation of the R716 CE gene on the calcium sensing receptor and the patient was diagnosed with Familial Hypocalciuric Hypercalcemia." (PMID 27957351, 2016). "Mutations that inactivate CaSR (i.e., result in loss-of-function) cause familial hypocalciuric hypercalcemia (FHH) and neonatal severe primary hyperparathyroidism (NSHPT)." (PMID 25420019, 2014). "In severe neonatal hyperparathyroidism, there is homozygous mutations in the CaSR gene in children born to consanguineous familial hypocalciuric hypercalcemia (FHH) parents." (PMID 23227372, 2012). "Human CASR mutations are known to be causative for primary hyperparathyroidism (HP) and familial benign hypocalciuric hypercalcemia (FHH)." (PMID 22527485, 2012). "Four female patients with familial hypocalciuric hypercalcemia with inactivating mutations in the CaSR gene were included in the treatment study." (PMID 22142470, 2011).
familial hypocalciuric hypercalcemia (continued). "The most common cause is parathyroid adenoma, usually due to single gland disease, but severe neonatal hyperparathyroidism can also occur due to biallelic mutations in the calcium sensing receptor gene (CASR) with hypocalciuric hypercalcemia." (PMID 21747852, 2011). "Heterozygous and homozygous CASR mutations that inactivate CASR are responsible, respectively, for familial hypocalciuric hypercalcemia, type 1 (also known as familial benign hypercalcemia) (OMIM #145980) and neonatal severe hyperparathyroidism (OMIM #239200)." (PMID 20661308, 2010). "Inactivating CaSR mutations develop hypocalciuric hypercalcemia and neonatal hyperparathyroidism, while activating CaSR gene mutations are associated with autosomal dominant hypocalcemia with Bartter syndrome type V." (PMID 23554644, 2010). "Familial hypocalciuric hypercalcemia due to a novel mutation in the calcium-sensing receptor gene was diagnosed in the proband and her two sons." (PMID 21034470, 2010). "However, cinacalcet is not always effective in all hyperparathyroidism patients, such as those with congenital CaSR mutations causing familial hypocalciuric hypercalcemia or neonatal hypoparathyroidism." (PMID 40164571, 2025). "Inactivating mutations in the CaSR gene, especially within the first 350 amino acids of the extracellular domain, lead to hypercalcemic disorders such as forms of primary hyperparathyroidism and familial hypocalciuric hypercalcemia (FHH)." (PMID 39336996, 2024). "Other less common causes of PHPT include parathyroid hyperplasia, often observed in multiple endocrine neoplasias types 1 and 2a (MEN1, MEN2A), and inactivating heterozygous mutations of the CaSR gene, associated with most cases of familial hypocalciuric hypercalcemia (FHH)." (PMID 39519190, 2024). "In one family with hypocalciuric hypercalcemia, which was confirmed by mutational analysis to be due to an inactivating mutation in the CaSR, subtotal parathyroidectomy revealed parathyroid gland hyperplasia/adenoma and corrected the biochemical signs of the disorder in seven of nine individuals." (PMID 35095753, 2021). "Additionally, further investigations are needed to delineate the extent of parathyroid radiofrequency ablation required for patients with hypocalciuric hypercalcemia caused by different types of inactivating CaSR mutations." (PMID 35095753, 2021). "Familial hypocalciuric hypercalcemia (FHH) is a rare autosomal dominant condition that occurs due to a variant in the calcium-sensing receptor gene (CaSR)." (PMID 37512002, 2023). "Familial hypocalciuric hypercalcemia (FHH) comprises a genetically heterogenic group: FHH1 [OMIM #145980] is caused by heterozygous inactivating mutations in the calcium-sensing receptor (CaSR) gene." (PMID 34659108, 2021). "Inactivating mutations in the CaSR are the cause of neonatal severe hyperparathyroidism in the case of homozygous mutations, and familial hypocalciuric hypercalcemia (FHH) in the case of heterozygous mutations." (PMID 33542868, 2021). "Familial hypocalciuric hypercalcemia (FHH) is an autosomal dominant disorder, associated with inactivating mutations of the calcium-sensing receptor (CaSR)." (PMID 27087013, 2016). "The similarity between lithium-induced hypercalcemia and familial hypocalciuric hypercalcemia (FHH), which is associated with inactivating mutations in the gene encoding the calcium-sensing receptor, has been underlined." (PMID 26542689, 2015). "Mutations in the CaSR gene cause familial hypocalciuric hypercalcemia (FHH) and neonatal severe hyperparathyroidism (NSHPT), two inherited conditions characterized by altered calcium homeostasis." (PMID 23799361, 2013). "Familial Hypocalciuric Hypercalcemia (FHH) is a generally benign disorder caused by heterozygous inactivating mutations in the Calcium-Sensing Receptor (CaSR) gene resulting in altered calcium metabolism." (PMID 22620673, 2012).
familial hypocalciuric hypercalcemia (continued). "A previous study has shown that an inactivating mutation of CASR causes familial hypocalciuric hypercalcemia (FHH), which leads to life-long hypercalcemia." (PMID 21966463, 2011). "Familial hypocalciuric hypercalcemia (FHH) is an autosomal dominant disorder caused by an inactivating mutation in the CASR gene, while Gitelman syndrome (GS) is an autosomal recessive renal tubular disorder resulting from a pathogenic mutation in the SLC12A3 gene." (PMID 40070587, 2025). "Acquired hypocalciuric hypercalcemia (AHH), which is analogous to FHH1 or NSHPT, has been reported to be also caused by autoantibodies against CaSR." (PMID 36099030, 2022). "Loss-of-function mutations of CaSR at 1 or both alleles inhibit CaSR signaling and cause increased PTH secretion, referred to as familial hypocalciuric hypercalcemia 1 (FHH1) and neonatal severe hyperparathyroidism (NSHPT), respectively." (PMID 36099030, 2022). "Inactivating mutations in CaSR lead to hypocalciuric hypercalcemia, which primarily includes FHH1 and NSHPT." (PMID 35095753, 2021). "Some mutants in the calcium-sensing receptor (CaSR) leading to familial hypocalciuric hypercalcemia and neonatal hyperparathyroidism can also be rescued using membrane-permeant allosteric agonists to recover protein functionality." (PMID 32392767, 2020). "Segregation analysis of parents evidentiated CaSR variant in heterozygosity, confirming the autosomal recessive inheritance of NSHPT and the familial hypocalciuric hypercalcemia (FHH) clinical state of the parents, although asymptomatic." (PMID 30376845, 2018). "Loss-of-function mutations of the CaSR gene present in homozygotes with neonatal severe hyperparathyroidism (NSHPT), while heterozygotes develop familial hypocalciuric hypercalcemia (FHH)." (PMID 27087013, 2016). "Inactivating mutations of the CASR lead to familial hypocalciuric hypercalcemia (FHH)." (PMID 27803672, 2016). "Previous studies show that mutations in the CASR gene can cause Mendelian disorders, wherein loss-of-function mutations lead to familial hypocalciuric hypercalcemia (FHH), while gain-of-function mutations can give rise to autosomal-dominant hypocalcemia or type 5 of Bartter syndrome." (PMID 25886283, 2015). "The most common cause is chronic kidney disease, but other causes include vitamin D deficiency, medications (such as lithium and thiazide diuretics), and familial hypocalciuric hypercalcemia (FHH) due to a heterozygous mutations of the calcium sensing receptor (CASR) gene." (PMID 21747852, 2011). "FHPT may also present as non-syndromic PHPT, which includes familial hypocalciuric hypercalcemia (FHH) forms (caused by variants of CASR, GNA11, or AP2S1), neonatal severe hyperparathyroidism, and other forms caused by several genes classified as familial isolated hyperparathyroidism (FIHP)." (PMID 37810884, 2023). "Familial hypocalciuric hypercalcemia (FHH, [OMIM #145980]) is recognized as a benign endocrine condition affecting PTH and calcium levels due to heterozygous inactivating mutations in the calcium sensing receptor (CaSR)." (PMID 34659108, 2021). "Taken together, the novel D99N homozygous mutation in the CaSR gene reduces CaSR activity, leading to reduced sensitivity of parathyroid cells to extracellular Ca2+ and abnormal PTH secretion, thereby causing more severe hypocalciuric hypercalcemia." (PMID 35095753, 2021). "Nonetheless, familial hypocalciuric hypercalcemia (FHH) patients are found to have a unique variant of the CaSR gene even though they do not have hyperparathyroidism." (PMID 33804544, 2021). "Familial hypocalciuric hypercalcemia (FHH) is a mostly benign condition of elevated calcium and PTH levels based on a hyposensitive calcium sensing receptor (CaSR) in FHH 1 or its downstream regulatory pathway in FHH2 and FHH3." (PMID 35566721, 2022).
familial hypocalciuric hypercalcemia (continued). "It is essential to exclude familial hypocalciuric hypercalcemia (FHH), a rare autosomal dominant disorder with three identified variants leading to the abnormal function of the CaSR, as surgery is not indicated in the presence of FHH." (PMID 33918966, 2021). "As already mentioned, the physiological significance became apparent when various inherited disorders like familial hypocalciuric hypercalcemia (FHH) and neonatal severe hyperparathyroidism (NSHPT) were found to be caused by loss-of-function mutations in the CaSR gene." (PMID 32117726, 2020). "The diseases associated with inactivate receptors include cases of Familial Hypocalciuric Hypercalcemia (FHH) and Neonatal Severe Hyperparathyroidism (NSHPT) while the disorders associated with the CaSR activating mutations include Autosomal Dominant Hypocalcemia (ADH) and Bartter syndrome type V." (PMID 27746744, 2016). "Familial hypocalciuric hypercalcemia (FHH) is an autosomal dominant disorder, familial hypocalciuric hypercalcemia type 1 (FHH1) is the most prevalent form of FHH and is caused by an inactivating mutation in the CASR gene, resulting in a loss of function of the calcium-sensing receptor (CaSR)." (PMID 40070587, 2025).